XBP1 (X-box binding protein 1)
Diseases named in the same sentence as XBP1 in open-access papers (continued):
Sharing a sentence is not in itself a finding about the gene and the disease.
tumor (continued). "The clinical + RNA model contains eight total features, including tumor stage and five of the same features from the RNA-only model (IgG, Green7, XBP1, Unknown8, and Red18)." (PMID 40057511, 2025). "XBP1 is persistently activated in tDCs, disrupting their homeostasis and impairing their ability to present antigens, thereby fostering local immunosuppression and contributing to immune evasion by tumor cells." (PMID 40278350, 2025). "Moreover, our results demonstrate that pharmacological inhibition of the IRE1α/XBP1 arm of the UPR ameliorates the skeletal muscle wasting in response to KPC tumor growth." (PMID 40655023, 2025). "Interestingly, muscle-specific ablation of XBP1 diminished the mRNA levels of multiple molecules of UPS or autophagy in KPC tumor-bearing mice (Fig. EV3A,B)." (PMID 41249735, 2025). "Moreover, XBP1 promoted tumor growth and metastasis by binding to the GNL3 (G protein nucleolar 3—a nucleolar protein involved in cell proliferation, cell cycle, and invasion) promoter and fostering its expression." (PMID 41228282, 2025). "Our RNA-seq analysis showed that the gene expression of multiple molecules involved in ERAD is upregulated in the skeletal muscle of KPC tumor-bearing mice and muscle-specific deletion of XBP1 dampens the expression of ERAD-related genes in response to KPC tumor growth (Fig. EV4C)." (PMID 41249735, 2025). "Importantly, targeted ablation or pharmacological inhibition of XBP1 significantly reduced tumor-induced increase in oxidized proteins in skeletal muscle of mice." (PMID 40655023, 2025). "In RMS, both the HSP70 (heat shock 70 kDa protein) inhibitor MAL3-101 and the p97 (valosin containing protein) ATPase inhibitor CB-5083 trigger robust UPR activation, marked by increased eIF2α phosphorylation, ATF4 and CHOP upregulation, and XBP1 splicing, thereby promoting tumor cell death." (PMID 41228282, 2025). "Our RNA-seq analysis showed that the gene expression of multiple molecules involved in ERAD is upregulated in the skeletal muscle of KPC tumor-bearing mice and muscle-specific deletion of XBP1 dampens the expression of ERAD-related genes in response to KPC tumor growth." (PMID 40655023, 2025). "However, there was a modest but significant reduction in the number of KPC cells by day 5 of 4μ8C treatment (Fig. EV5A) suggesting that inhibition of the IRE1α/XBP1 signaling can potentially inhibit KPC tumor growth in vivo." (PMID 41249735, 2025). "However, inhibiting XBP1 expression enhances the antitumor activity of tumor‐infiltrating CD8+ T cells." (PMID 40035165, 2025). "We next investigated whether targeted ablation of XBP1 affects oxidative stress in skeletal muscle in response to KPC tumor growth." (PMID 40655023, 2025). "XBP1 depletion in tumor cells has been shown to inhibit cell proliferation." (PMID 40105652, 2025). "Furthermore, genetic inhibition of XBP1 or pharmacological targeting of IRE1α using STF-083010 enhanced CD8+ T cell anti-tumor activity that resulted in reduced lung metastasis of tumor bearing mice." (PMID 41372991, 2025). "By regulating the activity of these immune cells, XBP1 may influence immune surveillance and the tumour therapeutic response and play a role in tumour immune escape." (PMID 40046334, 2025). "Interestingly, muscle-specific ablation of XBP1 diminished the mRNA levels of multiple molecules of UPS or autophagy in KPC tumor-bearing mice." (PMID 40655023, 2025). "Therefore, the small molecule inhibitor targeting IRE1-α and XBP1 to suppress UPR is considered as an important agent for tumor treatment and recurrence." (PMID 38500768, 2024). "Forwardly, we went on to testify whether the activation of IRE1α-XBP1 axis in tumor mediates the effect of systemic administration of HA15 on tumor growth and anti-tumor immunity in mice." (PMID 38291473, 2024).
tumor (continued). "Interestingly, XBP1 can simultaneously regulate the expression of multiple immune checkpoint molecules, such as PD1, LAG3, and HAVCR2, in some types of tumours, suggesting that XBP1 is a potential target for overcoming immunotherapy resistance." (PMID 38297380, 2024). "Inhibition of IRE1α-XBP1 signalling can attenuate cancer cell adaptation to ER stress and augment ER stress, which promotes tumour cell apoptosis; this method could be used as an anticancer strategy." (PMID 38297380, 2024). "In addition, HA15 treatment also resulted in robust increase of both Granzyme B+ and IFN-γ+ CD8+T cells in TME compared with control, but the knockdown of either IRE1α or XBP1 in tumor cells significantly mitigated this facilitative effect." (PMID 38291473, 2024). "Suppressing XBP1 expression can reduce tumor cell viability and drug resistance." (PMID 39439891, 2024). "Furthermore, tumor DCs with inactivated XBP1 can enhance the functionality of lymphocytes, such as the maturation of cytotoxic T lymphocytes and memory T lymphocytes." (PMID 39080273, 2024). "This study showed that targeting the XBP1-mediated ER stress response could significantly inhibit tumour growth and enhance anticancer immunity, thus providing a unique approach to cancer immunotherapy." (PMID 38297380, 2024). "Perturbation of the IRE1α/XBP1 axis or cholesterol biosynthesis in the tumor could prevent MDSCs from acquiring immunosuppressive function in murine melanoma and colon cancer models." (PMID 37067519, 2023). "Altogether, these data show that double ablation of the IRE1/XBP1 axis in DCs does not alter the course of tumor growth, whereas single XBP1 deficiency in DCs results in mild changes in tumor growth and T cell effector/exhausted profiles at the tumor site." (PMID 37346037, 2023). "In addition to HIF-1, the expression of X-Box Binding Protein 1 (XBP1), an endoplasmic reticulum stress-regulating transcription factor, also increases and plays a crucial role in TNBC cells, because XBP1 supports tumor stem cell proliferation in TNBC." (PMID 37511489, 2023). "Moreover, a human tumor xenograft model also showed that IRE1α/XBP1 induced a proangiogenic response in a VEGFA-independent manner." (PMID 37008067, 2023). "Moreover, siRNA-mediated silencing of XBP-1 or IRE1A prior to exposure of DLD-1 cells to hypoxia significantly reduced the number of metastatic tumor nodules that these cells formed after injection into NOD/SCID mice." (PMID 36831485, 2023). "Moreover, SIRT7 up-regulation eradicated anti-tumor immunity by promoting PD-L1 expression via the IRE1α-XBP1 axis." (PMID 36918544, 2023). "Furthermore, IRE1/XBP1 ablation in tumor cDC1s controls a discrete set of genes related to proteostatic programs without altering pro-tumorigenic programs seen in other tumor myeloid cell subsets." (PMID 37346037, 2023). "The authors also presented evidence that this phenomenon is specific to GVHD since the T cell response within the tumor was not impacted by XBP-1 deficient DCs." (PMID 37744326, 2023). "The present data revealed that ASCs in tumour tissues showed up‐regulated expression of XBP1, which is a canonical marker of ASCs, compared with expression in normal tissues, and the proportion of ASCs in tumour tissues with NACT was significantly larger than that in normal tissues." (PMID 36650114, 2023). "Shp2f/fLysMCre MDSCs also exhibited lower expression of Msr1, which promotes neutrophil netosis, a protumorigenic process, and Xbp1, a classical marker of the unfolded protein response, which polarizes tumor-infiltrating myeloid cells to highly immunosuppressive MDSC20." (PMID 36581713, 2023). "In addition, increased ROS production in tumor-infiltrating dendritic cells (TDCs) excessively activates IRE1/XBP1." (PMID 37790807, 2023).
tumor (continued). "In fact, in this kind of tumour, XBP1 is co-expressed with the oestrogen receptor." (PMID 36675080, 2023). "From animal studies, it was discovered that XBP1 is important for tumour growth in vivo." (PMID 36675080, 2023). "In addition, XBP-1 co-localizes with hypoxia markers in tumors and the loss of XBP-1 increases the sensitivity of tumor cells to hypoxia-induced apoptosis and inhibits tumor growth, implicating XBP-1(S) as a critical survival factor under hypoxic conditions." (PMID 36831485, 2023). "Thus, XBP1 can drive tumour progression in TNBC and ER-positive breast cancer via distinct mechanisms due to direct interaction with unique transcription factors and crosstalk with different signalling nodes." (PMID 38203358, 2023). "Silencing of XBP1 in tDC results in enhanced T cell anti-tumor immunity." (PMID 37395796, 2023). "Furthermore, we systematically correlated XBP1 and immunological characteristics in the BC tumour microenvironment (TME) using TISIDB, TIMER, GSE25055, GSE25056 and TCGA dataset." (PMID 35543228, 2022). "Moreover, high expression of XBP1-s positively correlates with tumor progression, poor prognosis, and drug resistance." (PMID 35269888, 2022). "XBP1 is highly expressed in cells and tissues of various cancers and is widely involved in tumour progression and metastasis via regulating a diverse array of genes involved in cell survival, apoptosis, autophagy, metastasis, invasion, drug resistance, lipid metabolism and immunoregulation." (PMID 35543228, 2022). "XBP1 mRNA levels in tumour tissue were higher than in normal and tumour adjacent tissues." (PMID 35543228, 2022). "Therefore, blocking XBP1 in CD8+ T cells or decreasing cholesterol synthesis in tumor cells restores the cytotoxic activity of tumor-infiltrating CD8+ T cells in lung tumor-bearing mice." (PMID 35945203, 2022). "XBP1-s is also involved in the increase of tumor cells’ drug resistance." (PMID 35269888, 2022). "It has been demonstrated that ascites fluid collected from ovarian cancer patients could activate IRE1α-XBP1 ER stress in T cells to inhibit mitochondrial function and anti-tumor immunity." (PMID 36147929, 2022). "Therefore, the authors have proved that blockade or silencing of XBP1 makes TADCs regain the capability of immunostimulatory response and restriction towards tumor." (PMID 36172157, 2022). "XBP1 mRNA expression level was correlated with tumour stage." (PMID 35543228, 2022). "Furthermore XBP1-u also exerts its anti-tumor function by promoting FoXO1 degradation, thereby inhibiting tumor cells autophagy." (PMID 35269888, 2022). "Numerous studies have shown that ERS can regulate the immune function of DCs, including cytokine production, DC maturation, antigen presentation and tumour immune response, by using an inositol-requiring enzyme 1 α/X-box-binding protein 1 (IRE1α/XBP1) signalling axis and PKR-like ER kinase (PERK)." (PMID 35883755, 2022). "However, abnormal activity of XBP1 affected normal cell proliferation, apoptosis, metastasis, and ultimately tumorigenesis and tumor progression." (PMID 35754792, 2022). "XBP1-s downregulation in these cancer cells can increase the inhibitory effect of estrogen receptor antagonists; hence, XBP1-s is a potential target for overcoming the tumor cells’ drug resistance problem." (PMID 35269888, 2022). "Notably, tumor-infiltrating macrophages in tumor-bearing Ern1 (-/-) mice had a marked reduction in spliced Xbp1, Il-23p19, Arg1 and Cd274 gene expression compared to their Ern1 fl/fl counterpart." (PMID 35237269, 2022). "Indeed, small molecules targeting the XBP1-s pathway have been reported as potential anti-tumor therapeutic agents." (PMID 35269888, 2022). "XBP1 is regarded as the fuel of tumorigenesis and tumor cell progression." (PMID 36172157, 2022). "XBP1s is increased in TNBC cells; however, XBP1 silencing inhibits tumor growth and invasiveness." (PMID 34356855, 2021).
tumor (continued). "Therapeutic XBP1 gene editing using AAV2-sgXBP1 enhanced the anti-tumor activity." (PMID 34667145, 2021). "Accordingly, mice that bear OvCa and lack XBP1 selectively in T cells demonstrate superior anti-tumor immunity, delayed malignant progression, and increased overall survival; interestingly, the role of XBP1 in NK cells may be opposite." (PMID 34248988, 2021). "Finally, the Myd88L252P tumor gene expression profile not only highlights the canonical NF-κB p65/RelA activation pathway and proliferation, but also strikingly shares an Xbp1 centered lymphoplasmacytic B-cell differentiation signature with MYD88L265P WM." (PMID 34017329, 2021). "Interestingly, GBM cells showed a significant upregulation of the spliced XBP1 isoform (s-XBP1) compared with non-tumor RPE-1 cells that displayed instead a significant increase in the expression of the unspliced XBP1 transcript (u-XBP1)." (PMID 34740374, 2021). "Then, the role of XBP1 in TAMs in tumor progression was evaluated via AOM-DSS model." (PMID 34667145, 2021). "However, our results showed that targeting XBP1 in TAMs were more effective due to its dual function of inhibiting tumor-promoting cytokines and recognition signals." (PMID 34667145, 2021). "This study also elucidated the regulatory network of LINC00963/miR-320a/XBP1 and its biological function in tumor development, suggesting that both LINC00963 and miR-320a could be potential therapeutic targets for the molecular targeted therapy of DLBCL." (PMID 34112145, 2021). "We found our RNA NPs could deplete XBP1 expression and suppress tumor growth after intravenous administration." (PMID 33413427, 2021). "Targeting XBP1 may help to restore the metabolic fitness and anti-tumor capacity of T cells in cancer hosts." (PMID 34248988, 2021). "Since XBP1 is a key molecule affecting tumor APVT formation, tumor growth and clinical prognosis of PCNSL patients, small molecules targeting this molecule might be able to prevent growth of the malignancy and improve clinical outcomes." (PMID 34093792, 2021). "Inhibiting XBP1 or reducing cholesterol in CD8+ T cells effectively restores anti-tumour activity." (PMID 34202553, 2021). "In mice, XBP1 knocks out severely impaired tumour growth during hypoxia." (PMID 34943783, 2021). "Furthermore, we evaluated the expression of CXCL12 and its receptor CXCR4 as well as some XBP1 pathway molecules in tumor cells under different culture condition." (PMID 34093792, 2021). "Accumulating evidence supports a direct role of XBP1 in tumor invasion and metastasis." (PMID 34418985, 2021). "Concomitantly, deletion of Xbp1 in DCs promoted an anti-tumor response." (PMID 35069537, 2021). "Our work demonstrates for the first time that in a cohort of patients with NSCLC, intra-tumor IRE1 splicing activity of XBP1 mRNA may impact tumor phenotypes and outcomes." (PMID 32576923, 2020). "Furthermore, XBP1, a multimodal transcription factor associated with MHC II regulation along with the ER stress response was found to impede tumor immunogenic cell death in a colorectal cancer model." (PMID 33348579, 2020). "At the same time, XBP1 activation can in turn induce a lipid biosynthetic programme, which results in the accumulation of LDs and blunted antigen presentation, leading to a reduced ability to control tumour growth." (PMID 32003505, 2020). "Nonetheless, XBP1 promotes the progression of triple-negative breast cancer (TNBC) through synergy with hypoxia inducible factor-1 alpha (HIF1α) to support tumor-initiating cell function and the metastatic ability of cancer cells under adverse environmental conditions." (PMID 33267910, 2020). "The fact that the IRE1α/XBP1 axis also regulates PD-L1 expression points to the UPR as a general mechanism for immune dysregulation at the tumor and immune cells interface with myeloid cells, ultimately impairing the function of tumor-specific T cells with loss of local immune surveillance." (PMID 32520957, 2020).
tumor (continued). "Mechanistically, XBP1 boosts triglyceride production and further widens the overloading of lipids, therefore disturbing the machinery of antigen presentation and blunting anti-tumor response." (PMID 32178254, 2020). "In contrast, CD4 T cells exposed to low glucose in the tumor microenvironment undergo IRE1/XBP1-mediated ER stress, which reduces mitochondrial respiration by limiting the expression of glutamine carriers on the membrane and therefore blunting glutamine oxidation." (PMID 32178254, 2020). "Thus, the IRE1α/Xbp1 axis drives the polarization of macrophages in the tumor microenvironment initiating a complex immune dysregulation leading to failure of local immune surveillance." (PMID 32520957, 2020). "Likewise, we found that XBP1 was upregulated in GBC tissues compared with adjacent non-tumor tissues." (PMID 32793479, 2020). "We observed reduced Xbp1 mRNA splicing in B16F10(CAV1) compared to B16F10(Mock) ex-tumor cells." (PMID 32811828, 2020). "Besides, the ratio of spliced to total XBP1 was highest in samples collected directly from breast cancerous tissue as compared to luminal samples or normal tissue surrounding a tumor." (PMID 31491919, 2019). "Additionally, XBP1 depletion in tumor-infiltrating DCs confers immunostimulatory and anti-tumoral characteristics on tumor-infiltrating DCs in vivo." (PMID 31739582, 2019). "Remarkably, the combined Creb3l2 plus XBP1 expression in the tumor-derived AtT-20 cells led to a shift of energy metabolism from glycolysis to oxidative phosphorylation, resulting in more efficient ATP production and providing for support of heavy protein synthesis." (PMID 31481663, 2019). "Additionally, in hepatocellular carcinoma, the detection of XBP1 in tumour samples positively correlates with vimentin and negatively with E-cadherin." (PMID 31071975, 2019). "Lastly, since we showed that the levels of PRKCSH mRNA were elevated in several tumor tissues, we checked whether the expression levels of XBP1 target genes were elevated in human tumors." (PMID 31320625, 2019). "XBP1 activation, in turn, induces a lipid biosynthetic program that results in the accumulation of LBs and blunted antigen presentation, leading to a reduced ability to control tumor growth." (PMID 31073300, 2019). "Together with the tumor size and the survival data, these experiments confirmed that XBP1+/RIDD− tumor cells yielded the most aggressive tumors whereas injecting XBP1−/RIDD+ tumor cells resulted in very small tumors, thereby confirming the results observed in patients’ tumors." (PMID 29311133, 2018). "Besides, Benjamin Drogat demonstrated that the IRE-1α-XBP1 pathway contributes to ischemia-mediated angiogenesis and tumor growth in vivo." (PMID 29933620, 2018). "The knockdown of XBP1 in TNBC cells caused a significant reduction in the expression of HIF1α target genes, such as vascular endothelial growth factor A (VEGFA), a key mediator of tumour angiogenesis." (PMID 30248920, 2018). "Together, these studies show that XBP1 is important for TNBC tumour initiation and progression." (PMID 30248920, 2018). "During the anti-tumor immune response, the XBP1 pathway induces tolerance in DCs." (PMID 30355343, 2018). "With respect to the anti-tumor functions of toyocamycin, some reports noted that toyocamycin inhibited XBP1 splicing via a conformational change in IRE1α to attenuate the activation of XBP1." (PMID 29581854, 2018). "Furthermore, in CHP100 (the type 2 fusion of EWS/FLI1) which had a low XBP1 expression, toyocamycin exerted significant anti-tumor activities and also activated apoptosis." (PMID 29581854, 2018). "It is possible that certain fortilin mutations could make fortilin unable to bind IRE1α, thus activating the XBP1 homeostasis branch of the IRE1α pathway and facilitating tumor growth and propagation." (PMID 28550308, 2017).